FGF2 (fibroblast growth factor 2)
Diseases named in the same sentence as FGF2 in open-access papers (continued):
Sharing a sentence is not in itself a finding about the gene and the disease.
ischemia (54 papers, 2007 to 2025). A hypoperfusion of the BLOOD through an organ or tissue caused by a PATHOLOGIC CONSTRICTION or obstruction of its BLOOD VESSELS, or an absence of BLOOD CIRCULATION. "Lo-FGF-2 is well documented to be cardioprotective, preventing myocardial loss and contractile dysfunction during myocardial infarction and in ischemia-reperfusion scenarios." (PMID 29152091, 2017). "Finally, transgenic mouse models engineered to express only Hi- or only Lo-FGF-2 have shown that Hi-FGF-2 expression was associated with increased susceptibility to ischemia and reperfusion injury while Lo-FGF-2 exerted a protective effect." (PMID 24827991, 2014). "It would not be surprising that PKCδ could also associate with Cx43 in cardiomyocytes, as FGF2, PKCε, PKCδ and Cx43 have all been implicated in cardioprotection following ischemia." (PMID 20338032, 2010). "Inadequate angiogenesis is one of the causes of tissue ischemia, with T3 inducing myocardial angiogenesis through PDGF/Akt, αVβ3 integrin MAPK, FGF2, and TRβ mediation." (PMID 41451128, 2025). "This is underscored by the observation that while both FGF1 and FGF2 reduced skin flap necrosis and ischemia in a rat model, FGF2 was more potent." (PMID 38001622, 2023). "In our experimental IR condition, the detection of elevated FGF2 in the surrounding tissue upon ischemia is indicative of its role in promoting angiogenesis in ischemic tissue." (PMID 32964031, 2020). "Another study showed that administered Hi-FGF-2 exerts acute post-conditioning-like cardioprotection against ischemia-reperfusion cardiac dysfunction and cell death." (PMID 29152091, 2017). "Future studies are necessary to determine the signaling mechanisms that mediate the cardioprotection provided by endogenous FGF2 in cardiac ischemia‐reperfusion injury in vivo." (PMID 25626875, 2015). "They found that animals treated with fibroblast growth factor-2 had greater blood flow recovery and produced a greater angiogenic response to ischemia." (PMID 25993289, 2015). "The main outcome of this work is that the subacute administration of zinc increases the expression of CCL2, CCR2, and growth factors (FGF2 and IGF-1) as well as preventing the loss of memory in the rats after transient hypoxia-ischemia." (PMID 26355725, 2015). "FGFs are able to promote angiogenesis and the formation of collateral circulation in cardiac or hind limb models of ischemia, the administration of FGF2 protein increases the formation of new vessels and collaterals." (PMID 25287126, 2014). "Following traumatic brain injury it has been shown to enhance SVZ and SGZ NSPC proliferation and increase the 4 weeks survival of newborn neurons, while FGF2 knockout mice show decreased hippocampal neurogenesis following seizure or ischemia." (PMID 23346046, 2012). "For example, miR-15a has been shown to inhibit angiogenesis in response to ischemia by reducing the activity of fibroblast growth factor 2 and VEGF, indicating that miR-15a may have protective effects in PDR." (PMID 41472886, 2025). "In addition, the administration of epidermal growth factors (EGF) and fibroblast growth factor 2 (FGF2) into the lateral ventricles of adult rats has also been shown to increase their BrdU and NeuN levels following ischemia." (PMID 38612470, 2024). "Exogenous administration of recombinant FGF2 in an ex vivo model of cardiac ischemia‐reperfusion injury has also been shown to improve functional recovery and reduce apoptosis and was found to increase phosphorylation of AKT and p70 S6 kinase as well as translocation of PKC isoforms." (PMID 25626875, 2015). "Studies have confirmed that FGF-2 could improve visual function in ischemia." (PMID 36532277, 2022). "VEGFa, SDF-1α, and FGF2 factors measured in the present study are responsible for angiogenesis, proliferation, migration, expressions of adhesion protein, and extracellular matrix reconstruction and are involved in initiating tissue repair and reperfusion following ischemia." (PMID 34367293, 2021).
ischemia (continued). "The Lo-FGF2 might be more critical in ischemia-induced cardiac injuries but not in DOX-caused cardiac dysfunction." (PMID 32354131, 2020). "We also examined the expression of NRP-1, FGF-2 and VEGF in the cortex of ischemic ipsilateral brain, and found the expression of NRP-1, FGF-2 and VEGF were increased by 7 days-ischemia compared with the sham-operated group (p<0.05; p<0.05; p<0.01)." (PMID 24979385, 2014). "Similar to VEGF and FGF-2, IL-1β, MCP-1, and SDF-1 are known as proangiogenic factors induced by ischemia." (PMID 22529991, 2012). "Rat hearts perfused with FGF-2 ex vivo show upregulated levels of phosphorylated Cx43 on S368 in intercalated discs suggesting a link between phosphorylation of Cx43 at PKC target sites such as S368 and FGF-2 induced cardioprotection against ischemia." (PMID 36712244, 2022). "In addition, the infusion of epidermal growth factors (EGF) and fibroblast growth factor-2 (FGF-2) in the lateral ventricle of adult rats also increased BrdU and NeuN levels after ischemia." (PMID 34768919, 2021). "Interestingly, a combined application of FGF-2 and VEGF increased tube formation of endothelial cells as compared to both factors alone, and a combination of MSC-derived VEGF, MCP-1, and IL-6 was identified as a driving mediator of angiogenesis in a hindlimb ischemia model." (PMID 37626914, 2023). "While assessing miR-210 function in the context of ischemia is of obvious physio-pathological relevance, we found that miR-210 expression was also necessary in the neo-angiogenic process stimulated by VEGF and FGF2 in Matrigel plugs, consistent with observations in non-ischemic adult mouse brains." (PMID 31878120, 2019).
diabetes (52 papers, 2009 to 2025). "Indicative of a dysfunctional signaling environment in situ, the expression of multiple growth factors and cytokines (Vegf-a, Fgf-2, Pdfg-a, and Sdf-1; P <0.02) as well their associated receptors (Cxcr-4, Fgfr-2, and Pdgfr-a; P <0.01) was significantly decreased in the setting of diabetes." (PMID 24943716, 2014). "The expressions of IL17A, ACE, TLR4, and IL6 are up-regulated with diabetes that promote the progression of gangrene, whereas the expressions of FGF2 and IGF1 are down-regulated." (PMID 40657379, 2025). "In our study, patients with diabetes and coexisting mood disorders exhibited higher levels of FGF-2 and FGF-23." (PMID 40943671, 2025). "HA@MnO2/FGF-2/Exos hydrogel generated a suitable milieu for activation of angiogenesis and epithelization, resulting in significantly better wound closure in diabetes." (PMID 39980588, 2025). "The expressions of IL17A, MMP2, IL10 and IL6 are up-regulated with diabetes that promote the progression of OP, whereas the expressions of FGF2 and VEGFA are down-regulated." (PMID 38250601, 2024). "Fibroblast growth factor 2 (FGF2) has been reported to play various roles, such as affecting anxiety psychology, regulating diabetes and related complications, inducing tumor growth, and participating in the regulation of cell proliferation." (PMID 38674344, 2024). "The role of FGF2 in the therapy of lung, neural, or vascular diseases, wound healing and diabetes or myocardial revascularization has been already studied." (PMID 34067330, 2021). "A trio of genes encoding angiogenic factors—FGF2, CXCL12 and LEP—were downregulated by diabetes (FGF2 an CXCL12, p < 0.01 vs control group; LEP, p < 0.05 vs control group)." (PMID 31001672, 2019). "Our data agree with a previous report of upregulated Fgf2 protein levels after 3 months of diabetes in the Sprague Dawley rat." (PMID 21249158, 2011). "Several studies have shown that FGFs, particularly FGF-2, FGF-19, and FGF-23, are altered in diabetes and may be associated with complications such as nephropathy and impaired wound healing." (PMID 40943671, 2025). "However, after 6 months of diabetes, Il33−/− retinas expressed significantly lower levels of Glul and higher levels of Bdnf, Cntf, Fgf2 and Ngf compared with the levels in WT retinas." (PMID 37671525, 2023). "Furthermore, the bioactive glass used was responsible for the production of VEGF and FGF2 which possess an important role in the process of wound healing, especially in diabetes." (PMID 37274157, 2023). "Of note, FGFR2 expression correlated significantly with neonatal sum of skinfolds and placental weight, which accords with a previous report showing a positive relationship between FGF2 and birth-weight and placental size in pregnancies complicated by diabetes." (PMID 34930438, 2021). "Our group has also had positive previous experiences of the use of genetic constructs containing the combination of VEGF and FGF2 genes in the treatment of chronic wounds (such as trophic ulcers in diabetes) and injuries to tendons or ligaments in domestic animals." (PMID 30931318, 2019). "Moreover, decreased growth factors such as insulin-like growth factor-I and fibroblast growth factor-2 are related to diminished bone formation during bone repair in diabetes." (PMID 24651693, 2014). "Moreover, our finding of reduced FGF-2 in patients with both diabetes and hypertension is notable." (PMID 40943671, 2025). "A statistically significant difference between controls and subjects with diabetes at baseline was observed in aqueous humor levels of the following cytokines: IL-10, IL-12p70, IL-12p40, IL-15, EGF, FGF-2, VEGF, MIP-1β, MCP-3 and MDC (p < 0.05; p < 0.001)." (PMID 30410092, 2018). "This study also demonstrated some strain selectivity regarding the extent and variability of the effect of diabetes on growth factors levels such as vascular endothelial growth factor (VEGF) and fibroblast growth factor 2 (FGF-2;)." (PMID 24349305, 2013).
diabetes (continued). "Given the clinical relevance of glycemic control, Spearman’s rank correlation analysis was conducted to assess the relationship between glycated hemoglobin (HbA1c) levels and concentrations of selected fibroblast growth factors (FGF-2, FGF-19, FGF-22, and FGF-23) in patients with diabetes (n = 73)." (PMID 40943671, 2025). "Similar to FGF-2, lower FGF-22 levels were observed in patients with diabetes and hypertension; however, no prior reports have linked FGF-22 to hypertension." (PMID 40943671, 2025). "FGF-2, FGF-19, FGF-22, and FGF-23 likely significantly impact diabetes and its complications." (PMID 40943671, 2025). "When analyzed separately by diabetes type, in patients with type 2 diabetes (n = 73), age showed negative correlations with FGF-2 (ρ = −0.27, p = 0.022) and FGF-22 (ρ = −0.32, p = 0.005)." (PMID 40943671, 2025). "In light of these limitations, further large-scale studies with more homogeneous cohorts, incorporating medication tracking, and longitudinal follow-up are necessary to validate the current results and clarify the mechanistic and prognostic roles of FGF-2, FGF-19, FGF-22, and FGF-23 in diabetes." (PMID 40943671, 2025). "In this experiment, we found USCs-FGF2 increased endogenous VEGF protein expression, indicating the FGF2 modification may repair the VEGF signaling pathway in the corpora cavernosa of diabetic ED rats." (PMID 24663037, 2014). "More importantly, key genes of the respective pathways, such as AKT3, FGF2, FGF7, mitogen-activated protein kinase 4 (MAP3K4), MAP3K5, insulin receptor (INSR), AKT3, and mTOR, were also enriched in the analysis, thus explaining the link between diabetes and BCRL subjects in the present study." (PMID 36232660, 2022). "RSV also regulates fibroblast growth factor 2 (FGF2), a paracrine molecule that contributes to cardiac fibrosis by binding to its receptors, such as FGFR1 and heparan sulfate proteoglycans (HSPGs), on the surface of mCFs; from there, it subsequently exerts its antifibrotic ability in diabetes." (PMID 32256959, 2020). "Moreover, FGF2 and CXCL12 were reduced by diabetes at the protein level (p < 0.001)." (PMID 31001672, 2019). "Consequently, a refined selection comprising seven genes (MMP2, MMP9, IL17A, IL10, FGF2, IL6 and VEGFA) and eleven pharmacological agents has emerged, exhibiting promise in delivering therapeutic effects aimed at mitigating the occurrence of OP in individuals afflicted with diabetes." (PMID 38250601, 2024).
osteosarcoma (48 papers, 2002 to 2026). A usually aggressive malignant bone-forming mesenchymal neoplasm, predominantly affecting adolescents and young adults. "Circ001422 and miR‐195‐5p have been shown to increase FGF2 expression to accelerate osteosarcoma tumourigenesis and metastasis." (PMID 39039912, 2024). "In osteosarcoma, circ_001422 targeted miR-195-5p and promoted the progression and metastasis through the miR-195-5p/FGF2/PI3K/Akt axis." (PMID 36539807, 2022). "KDM4B is upregulated in osteosarcoma compared with normal tissues and can promote fibroblast growth factor 2 (FGF2) upregulation, which promotes the proliferation, migration, and invasion of osteosarcoma cells." (PMID 35186950, 2021). "Another report indicated miR-503 suppressed proliferation and migration through modulation of FGF2 in osteosarcoma cells." (PMID 28341855, 2017). "The FGF2-induced proliferation of G292 (osteosarcoma cell) was inhibited by APT-F2P more sensitively with an estimated IC50 value below 1 nmol/l." (PMID 27506449, 2016). "Here, we show that the Janus kinases JAK1, JAK2 and TYK2, but not their main downstream effectors STAT1, STAT3 or STAT5A/B, are required for FGF-2-mediated chemoprotection in U2OS osteosarcoma cells." (PMID 21625473, 2011). "They concluded that miR-646 may be a tumor suppressor in osteosarcoma via its direct target of Fibroblast Growth Factor 2 (FGF2)." (PMID 37719019, 2023). "While in our studies Spry4 wildtype protein failed to influence the activity of MAPK in WI-38 cells as well as in osteosarcoma-derived cells in response to FGF2 induction, the conversion of the serine at position 241 empowered the protein to interfere with FGF-mediated signal transduction." (PMID 33670044, 2021). "miR-646 can downregulate FGF2 and suppress osteosarcoma cell metastasis." (PMID 26650737, 2015). "The block of Fgf2 factor could modulate the progression of osteosarcoma." (PMID 28439237, 2017). "However, a previous study showed that knockdown of APE1 could markedly inhibit tumor angiogenesis by downregulating FGF2/FGFR3 in human osteosarcoma model." (PMID 28839218, 2017). "Besides, miR-646 was found to suppress osteosarcoma cell metastasis by downregulating FGF2." (PMID 28740507, 2017). "Fibroblast growth factor-2 (FGF-2) activates TYK2 to stimulate proliferation and protect osteosarcoma cells from chemotherapeutic drugs in vitro." (PMID 34439323, 2021). "Overexpression of KDM4C was found in non-small cell lung carcinoma and osteosarcoma, where upregulation of fibroblast growth factor 2, promoted by KDM4B/C modulates cell migration, invasion, and proliferation in osteosarcoma metastasis." (PMID 34778065, 2021). "The ability of the osteosarcoma cell line Saos-2 to induce new blood vessel formation by upregulation of angiogenic growth factors like VEGF165, FGF2, MMP2 and MMP9 has already been shown." (PMID 30986223, 2019). "Four ARGs-BRMS, COL4A2, FGF2, and OGT-were used to develop an RFS-predicting model, whereas seven ARGs-CD24, FASN, MMP2, EIF2AK3, ID2, PPARG, and PIK3R3-were used to develop an OS-predicting model in patients with osteosarcoma." (PMID 38217543, 2024). "As far as the detailed mechanism in osteosarcoma, JMJD2C could up-regulate the expression of FGF2 (fibroblast growth factor 2) and interact with FGF2, which is a prototypic growth factor and plays a promoting role in carcinogenesis." (PMID 29207681, 2017). "Although FHL2 silencing abrogated the positive effect of Wnt3a on osteosarcoma cell growth, this effect might be explained by overall reduced proliferation since FHL2 silencing also abrogated FGF-2-induced cell proliferation." (PMID 23383046, 2013). "In our study, TSP1 expression was stimulated in osteosarcoma cell lines by TGF-β1, not by other growth factors (VEGF, EGF, FGF-2), and this is accordance with previous study that TGF-β1 not EGF could stimulate TSP1 expression in osteosarcoma cell line MG63." (PMID 29100277, 2017).